FCGR1A (Fc gamma receptor Ia)
Diseases named in the same sentence as FCGR1A in open-access papers (continued):
Sharing a sentence is not in itself a finding about the gene and the disease.
cancer (continued). "Furthermore, FCGR1A was notably associated with infiltrating levels of CD4+ T cells, CD8+ T cells, B cells, macrophages, neutrophils, and dendritic cells in the four cancers (P < 0.05)." (PMID 33344503, 2020). "The significant differential expression of FCGR1A was observed in many cancer types." (PMID 33344503, 2020). "In summary, high FCGR1A expression leads to different outcomes in diverse cancers." (PMID 33344503, 2020). "And this gene indicated highly significant positive correlations with FCGR1A in four cancers." (PMID 33344503, 2020). "FCGR1A, a high-affinity FCGR expressed on the surface of myelomonocytic and dendritic cells, may serve as a prognostic marker associated with immune infiltration levels across various cancers." (PMID 39423857, 2025). "To determine whether FCGR1A affects cancer cell motility, we compared its expression levels in 3 OC cell lines (KGN, A2780, and SKOV3) and normal ovarian epithelial cells (IOSE80) and found that the expression of FCGR1A was greater in KGN and SKOV3 cells than in A2780 and IOSE80 cells." (PMID 38879666, 2024). "The prognostic impact and immune infiltration of FCGR1A in heterogeneous cancers remain unclear." (PMID 33344503, 2020). "This evidence may help us infer the correlation between FCGR1A and cancers." (PMID 33344503, 2020). "Several studies on FCGR1A (CD64) mainly focused on the diagnosis and distinction of infectious diseases, but rarely on cancer." (PMID 33344503, 2020). "We explored the correlation between FCGR1A and CASS4 in various cancer types through TIMER database." (PMID 33344503, 2020). "Also, FCGR1A is involved in many pathophysiological processes and is closely related to FCGR3A, SYK, and HCK in various cancers." (PMID 33344503, 2020). "FCGR1A is a novel finding, not reported previously in cancer, and may well play a role in mAb-based immunotherapy, based on the receptors’ potent cytotoxic effects and their capability to efficiently mediate antigen presentation." (PMID 34200100, 2021).
FCGR1A also shares sentences with these, for which no sentence is quoted: Neonatal sepsis (20 papers); acute myeloid leukemia (15); influenza (10); lupus (10); colitis (9); infectious disease (9); bacterial sepsis (8); Arthritis (7); autoimmune disease (7); pneumonia (7); schizophrenia (7); lymphoma (6); melanoma (6); Obesity (6); systemic inflammatory response syndrome (6); glioblastoma (5); myeloid leukemia (5); acute pancreatitis (4); acute promyelocytic leukemia (4); Alzheimer disease (4); Autoimmunity (4); fungal infections (4); inflammatory bowel disease (4); Multiple Myeloma (4); nephritis (4); neutropenia (4); pancreatitis (4); pulmonary TB (4); Stroke (4); Adenitis) (3).
A further 139 diseases each share a sentence with FCGR1A in 3 papers or fewer.